PANCR (PITX2 adjacent non-coding RNA)
Synonyms: RP11-380D23.2
Gene: Long non-coding RNA gene on chromosome 4 (110,511,761 to 110,616,031, reverse strand). Ensembl gene ENSG00000250103.
Diseases named in the same sentence as PANCR in open-access papers:
PANCR is named in the same sentence as 9 diseases in open-access papers, as found by Europe PMC text mining. Sharing a sentence is not in itself a finding about the gene and the disease. The quoted sentences say what the papers report.
Axenfeld-Rieger syndrome (1 paper, 2025). Axenfeld-Rieger syndrome (ARS) is a generic term used to designate overlapping genetic disorders, in which the major physical condition is anterior segment dysgenesis of the eye. "Notably, PANCR, a lncRNA located near the PITX2 gene, has been reported to be closely associated with Axenfeld-Rieger syndrome and tooth malformations." (PMID 40346090, 2025).
carcinoma in situ (1 paper, 2016). "However, a stepwise analysis of normal mucosa of high risk/no risk patients, dysplastic epithelium, carcinoma in situ, invasive squamous cell cancer, lymph node and distant metastases is needed to fully understand the role of PITX2 and PANCR methylation in development and progression of HNSCC." (PMID 27716615, 2016).
Obesity (1 paper, 2022). Accumulation of substantial excess body fat. "We identified two other DMRs in genes RPL28 and PANCR that have not previously been associated with adipogenesis or lower birth weight before but have appeared in several obesity or metabolism related studies." (PMID 35216435, 2022).
tumor (3 papers, 2016 to 2024). "As PITX2 and PANCR methylation were increased in tumor tissue, their potential as prognostic factor for OS was investigated by means of univariate Cox regression and Kaplan-Meier analysis." (PMID 27798672, 2016). "The comparison of PITX2 and PANCR DNA methylation in tumor tissue and normal adjacent tissue (NAT) revealed a significantly higher frequency of hypermethylation in cancer tissue (p < 0.001)." (PMID 27716615, 2016).
cancer (1 paper, 2016). A tumor composed of atypical neoplastic, often pleomorphic cells that invade other tissues. "Given the promising, albeit conflicting, data about PITX2 methylation and risk of disease progression in cancer, the methylation status of PITX2 and PANCR and its potential function as a prognostic biomarker was investigated in a well annotated HNSCC cohort." (PMID 27716615, 2016).
PANCR also shares sentences with these, for which no sentence is quoted: adenocarcinoma (1 paper); congenital glaucoma (1); glaucoma (1); head and neck squamous cell carcinoma (1).